S100A9 (S100 calcium binding protein A9)
Diseases named in the same sentence as S100A9 in open-access papers (continued):
Sharing a sentence is not in itself a finding about the gene and the disease.
liver cirrhosis (4 papers, 2015 to 2022). "One dramatically up-regulated protein S100A9 (ratio = 19) was further validated by ELISA in sera from liver cirrhosis (LC, HCC high risk population) and HCC patients (n = 47 for each group)." (PMID 27216119, 2016). "Further, we also detected and analyzed the S100A9 levels in CHB patients with and without liver cirrhosis." (PMID 29615081, 2018).
metastatic tumors (4 papers, 2021 to 2022). "S100A8 and S100A9 are among the most induced immune mediators and involve in tumor-stroma paracrine crosstalk inferred by single-cell RNA-seq from metastatic tumors." (PMID 35440136, 2022). "The same treatment of S100A9‐targeted CPMV was also effective when administered after lung metastatic tumor establishment (i.e., by significantly delaying tumor growth and improving overall survival rate)." (PMID 34519180, 2021). "However, macrophages in metastatic tumors had high expression of HLA-DQA2, KRT15, S100A8, and S100A9, and GO analysis showed that lipid catabolic process, myeloid leukocyte migration, and the regulation of cell activation were highly enriched." (PMID 36569924, 2022). "Taken together this suggests that S100A9 and S100A12 levels in blood could be markers of metastatic disease." (PMID 34067757, 2021).
multiple sclerosis (4 papers, 2018 to 2024). A progressive autoimmune disorder affecting the central nervous system resulting in demyelination. "S100A9 is also up-regulated in other diseases with a neuro-inflammatory component, including traumatic brain injury (TBI), post-operative cognitive dysfunction (POCD), and multiple sclerosis (MS); broadening the potential therapeutic applications of ORY-2001." (PMID 32469975, 2020).
nasal polyps (4 papers, 2010 to 2025). "Moreover, the up-regulation of S100a9 expression in the nasal polyp tissues of patients with CRSwNP compared to the inferior turbinate tissue of both healthy control and CRS without NP patients was reported in recent studies." (PMID 38678138, 2024). "Decreased expression of S100A8 and S100A9, members of the epidermal differentiation complex at chromosome 1q21, in epithelial cells from CRS patients with and without nasal polyps was recently reported." (PMID 20625511, 2010).
periodontal disease (4 papers, 2013 to 2024). "The proteins S100A8 and S100A9, which are produced by neutrophils and macrophages, can be found in plasma, but their levels in GCF may differ significantly during periodontal disease owing to the local inflammatory response and recruitment of those white cells." (PMID 24098404, 2013).
pneumococcal infection (4 papers, 2012 to 2023). Infections with bacteria of the species streptococcus pneumoniae. "Luminex-based analyses of pro- and anti-inflammatory cytokines showed significantly increased levels of CXCL1, CXCL2 and G-CSF in BALF of S100A9 KO mice as compared to WT mice on days 1 and 2 after pneumococcal infection." (PMID 37467233, 2023). "However, this inference remains speculative as loss of S100A9 has also been shown, albeit in a distinct model, to diminish control of pneumococcal infection due to impaired recruitment of neutrophils to the lung and reduced expression of pro-inflammatory cytokines." (PMID 31437249, 2019). "Studies of opioid abuse have shown that morphine treatment resulted in diminished secretion of the antimicrobial proteins, S100-A9 and S100-A8/A9, in lung tissue and samples of bronchoalveolar lavage fluid during the early stages of Streptococcus pneumoniae infection." (PMID 22860055, 2012).
preeclampsia (4 papers, 2022 to 2025). Preeclampsia is a hypertensive disorder of pregnancy that is characterized by new-onset hypertension with proteinuria presenting after 20 weeks of gestation, and depending on mild or severe forms may initially present with severe headache, visual disturbances, and hyperreflexia. "Currently, S100A8 and S100A9 are gaining increased attention as inflammatory markers of preeclampsia." (PMID 41155408, 2025). "However, elevated S100A9 levels have been observed in the plasma and placentas of patients with preeclampsia, a pregnancy-specific syndrome." (PMID 40861440, 2025). "We identified elevated levels of S100A9 in lysates of preeclampsia platelets." (PMID 35455936, 2022). "A regression model using five RNAs selected for ‘pregnancy hypertension’ (preeclampsia and gestational hypertension) yielded good predictive power with an AUC of 0.86, and like the present study, their proposed RNA panel included NAMPT (the remaining markers were MMP8, SRPK1, S100A9, and S100A8)." (PMID 35741140, 2022).
renal cell carcinoma (4 papers, 2015 to 2024). "This notion can be supported by finding of the overexpression of S100A8 and S100A9 by the cancer cells in renal cell carcinoma." (PMID 31582902, 2019). "In order to investigate the two members of the EF-hand Ca2+ binding protein S100 family, S100A8 and S100A9, in renal cell carcinoma (RCC), serum samples were collected from patients with RCC, transitional cell carcinoma in the kidney, benign renal masses and normal controls." (PMID 25673070, 2015).
Salmonella Infections (4 papers, 2015 to 2023). Infections with bacteria of the genus SALMONELLA. "We could hypothesize that PPAR pathway enrichment associated with increased expression of S100A9/12 at 7 dpi is involved in the increased Bacteroidetes and resistance to Salmonella infection in chicken." (PMID 36902251, 2023). "In this context, upregulation of S100a9 and Reg3g as well as elevated IL-22 serum levels during Salmonella infection suggesting alternative signaling pathways potentially mediated via STAT348." (PMID 34497340, 2022). "It is possible to suggest that the PPAR metabolic pathway and S100A9/12 are involved in the resistance to Salmonella infection in chicken through unknown mechanisms." (PMID 36902251, 2023). "Among the multiple genes detected in this study, EXFABP, S100A9/12, CEMIP, FKBP5, MAVS, FAM168B, HESX1, EMC6, and others were found as potential candidate gene and transcript (co-) factors for resistance to Salmonella infection." (PMID 36902251, 2023). "The functional role of S100A8/A9 in the host defense against murine Salmonella infection was limited however, given the fact that S100A9-/- mice were indistinguishable from WT mice with respect to survival, bacterial organ counts and inflammatory responses." (PMID 25860480, 2015).
sarcoidosis (4 papers, 2011 to 2024). Sarcoidosis is a multisystemic disorder of unknown cause characterized by the formation of immune granulomas in involved organs. "However, contrary to the observed elevation of MRP14/S100A9, serum levels of MMP1 and MMP7 were notably higher in IPF compared to fibrotic sarcoidosis." (PMID 39281278, 2024).
septic shock (4 papers, 2019 to 2025). Shock caused by infection; frequently caused by gram negative bacteria, although some cases have been caused by other bacteria, viruses, fungi, and protozoa; characterized by fever, chills, tachycardia, tachypnea, and hypotension. "The AUC for S100A9 combined with lactate and APACHE II in estimating the risk of septic shock improved from 0.74 (95% CI 0.68–0.79, P < 0.001) to 0.81 (95% CI 0.76–0.86, p < 0.001), and the sensitivity for detecting septic shock was also improved (from 65.50% to 74.20%)." (PMID 40478888, 2025). "We measured plasma levels of two DAMPs, S100A8/S100A9 and S100A12 during the first 24 h of admission of septic shock patients." (PMID 31666644, 2019). "Upon ICU admission, individuals diagnosed with septic shock exhibited higher serum S100A9 levels against the septic non-shock patients, and the difference between the two groups was statistically significant (p < 0.001)." (PMID 40478888, 2025).
squamous cell carcinoma (4 papers, 2013 to 2025). A carcinoma arising from squamous epithelial cells. "Aberrant expression of S100A8/S100A9 complex was also detected in a variety of cancer tissues, including in squamous cell carcinomas of the esophagus, oral cavity, and cervix." (PMID 31208368, 2019). "The expression level of S100A8/S100A9 measured in three squamous cell carcinomas (SCC) cell lines and their corresponding xenografts, as well as in 257 SCC tissues." (PMID 31208368, 2019). "Therefore, we examined the expression of S100A8/S100A9 in squamous cell carcinoma cell lines A431, HCC94 and FaDu." (PMID 31208368, 2019). "Mucosal epithelium, where squamous cell carcinoma originates from, is known to have high level of S100A8 and S100A9 at physiological conditions, which was reported to be present in the tumor as well." (PMID 32733643, 2020). "Calprotectin or S100A8/A9, a heterodimeric complex of calcium-binding proteins S100A8 (MRP8 or calgranulin A) and S100A9 (MRP14 or calgranulin B), may play a role in growth regulation and tumorigenesis in HNSCC and other squamous cell carcinomas (SCCs)." (PMID 23874958, 2013).
subarachnoid hemorrhage (4 papers, 2023 to 2025). A serious neurological disorder characterized by intracranial hemorrhage into the subarachnoid space. "Notably, the cerebrospinal fluid level of S100A9 was higher in patients with subarachnoid hemorrhage (SAH) and correlated with the short-term prognosis of patients after SAH." (PMID 40320180, 2025).
allergic asthma (3 papers, 2024 to 2025). A asthma with a basis in a pathological type I hypersensitivity reaction. "Overexpression of S100A9 can exacerbate lung injury and inflammation in patients with allergic asthma, whereas inhibition of S100A8 and S100A9 can stabilize macrophage polarization and inhibit glycolysis to improve allergic asthma." (PMID 40880642, 2025). "To verify the role of S100A8 and S100A9 in allergic asthma mice, we assessed respiratory function, observed pathological damage to lung tissue, and measured the levels of inflammatory cells and cytokines in BALF." (PMID 38646478, 2024). "To better understand the roles of S100A8 and S100A9 in the pathogenesis of allergic asthma, we used ovalbumin (OVA)-induced MH-S cells, and OVA-sensitized and challenged mouse models (wild-type male BALB/c mice)." (PMID 38646478, 2024). "Our study highlighted the potential of inhibiting S100A8 and S100A9 to ameliorate allergic asthma by stabilizing macrophage polarization and inhibiting glycolysis." (PMID 38646478, 2024). "The in vivo results of our study demonstrated that the knockdown of S100A8 or S100A9 inhibited M1 and M2 macrophage polarization and improved respiratory function and lung injury in mice with allergic asthma." (PMID 38646478, 2024). "S100A8 and S100A9 play critical roles in allergic asthma pathogenesis by promoting macrophage perturbation and glycolysis through the TLR4/MyD88/NF-κB signaling pathway." (PMID 38646478, 2024). "Our study highlights that S100A8 and S100A9 play critical roles in the pathogenesis of allergic asthma by promoting macrophage perturbation and glycolysis through the TLR4/MyD88/NF-κB signaling pathway." (PMID 38646478, 2024). "S100A8 and S100A9 may be involved in the regulation of macrophage polarization, glycolytic metabolism, and pyroptosis in allergic asthma." (PMID 38646478, 2024). "In particular, S100A9 overexpression exacerbates lung injury and inflammation in allergic asthma." (PMID 38646478, 2024). "For instance, S100A9 knockout mice, which lack the subunit that stabilizes the functional S100 protein heterodimer, exhibited attenuated hallmarks of asthma, including airway inflammation, airway hyperresponsiveness, and airway remodeling, in a murine model of allergic asthma." (PMID 40723384, 2025). "Inhibition of S100A8 and S100A9 may be a potential therapeutic strategy for allergic asthma." (PMID 38646478, 2024). "Additionally, the glycolysis inhibitor 3-BP (HK2 inhibitor) antagonized S100A9 overexpression, effects, suggesting that the regulation of glycolysis plays a critical role in the involvement of S100A9 in allergic asthma and HK2 might be a target of S100A9." (PMID 38646478, 2024). "In murine models of allergic asthma, deletion or inhibition of S100A8 or S100A9 has been shown to reduce airway inflammation, eosinophilic infiltration, and structural remodeling." (PMID 40723384, 2025). "OVA-induced allergic asthma increased all levels, whereas S100A8 and S100A9 knockdown decreased the levels in OVA-sensitized and challenged mice (p < 0.01)." (PMID 38646478, 2024). "In addition, 3-BP, an inhibitor of HK-II, antagonized the effects of S100A9 overexpression, suggesting that HK-II is a key gene involved in the S100A8 and S100A9 regulation of glycolysis in mice with allergic asthma, which warrants further investigation." (PMID 38646478, 2024). "Flow cytometry results showed that the proportion of M1 (CD86+) and M2 (CD206+) macrophages was decreased in OVA-induced allergic asthma mice with 3-BP intervention, whereas they increased in OVA-sensitized and challenged mice with S100A9 overexpression (p < 0.01)." (PMID 38646478, 2024). "The TLR4/MyD88/TRIF/NF-κB signaling pathway and ACLY activity were inhibited in OVA-induced MH-S cells with knockdown of S100A8 or S100A9 and allergic asthma mice, suggesting that knockdown of S100A8 or S100A9 inhibits glycolysis by suppressing the TLR4/MyD88/TRIF/NF-κB signaling pathway." (PMID 38646478, 2024).
astrocytoma (3 papers, 2020 to 2025). "They found that CD163 and CD68, as well as S100A9 rates were elevated in dexamethasone-treated grade I astrocytoma and GBM compared to normal brain tissue and grades II and III tumors." (PMID 33204365, 2020).
Cachexia (3 papers, 2022 to 2026). Severe weight loss, wasting of muscle, loss of appetite, and general debility related to a chronic disease. "Therefore, blood levels of the identified cachexigenic factors might help identify early PC individuals with unexplained weight loss, and therapies targeting S100A9 activity might attenuate both PC-induced cachexia and PCDM, reducing PC-induced complications." (PMID 37280516, 2023). "Collectively, our findings reveal that BAT undergoes functional reprogramming into a senescent and secretory tissue in cancer cachexia, with adipocyte-derived S100A9 acting as a novel pro-cachectic mediator." (PMID 42069727, 2026). "The combined in-vitro and clinical findings provide strong evidence that S100A9 contributes to PC-induced cachexia." (PMID 37280516, 2023). "In conclusion, in vitro atrophic effects of S100A8, S100A9, and S100A8/A9 suggest their potential as pathogenic factors of PC-induced cachexia." (PMID 37280516, 2023). "Atrophic effects of S100A8, S100A9, and S100A8/A9 indicated them as potential pathogenic factors of PC-induced cachexia." (PMID 37280516, 2023). "Whereas in a previous study the association between serum S100A9 level and cachexia-related parameters was not statistically significant, this study included more PC patients (n = 143) compared with the previous study (n = 88), resulting in greater statistical power." (PMID 37280516, 2023). "Tumors of PC patients with cachexia had markedly elevated expression of S100A8 (P = 0.003) and S100A9 (P < 0.001)." (PMID 37280516, 2023). "PC patients with cachexia had significantly higher serum levels of S100A8, S100A9 and S100A8/A9." (PMID 37280516, 2023). "Taken together, changes in IL-6, TNF-α or other pro-inflammatory factors reported previously might be the consequences of the complex tumor-incited immunological responses mediating cachexia, whereas our results support that S100A8, S100A9 and S100A8/A9 are potential drivers of PC-induced cachexia." (PMID 37280516, 2023). "Patients with PC-induced cachexia at diagnosis had significantly higher serum levels of S100A8, S100A9 and S100A8/A9 compared with PC patients without cachexia, patients with pancreatitis, and healthy controls." (PMID 37280516, 2023). "Although it is well known that systemic inflammation drives cancer cachexia and S100A8, S100A9, and S100A8/A9 have potent proinflammatory functions, the link between these factors and PC-induced cachexia has not been discovered previously." (PMID 37280516, 2023). "In addition, serum levels of either S100A8, S100A9, or S100A8/A9 did not correlate with those of IL-6 or TNF-α in PC patients with cachexia (n = 80)." (PMID 37280516, 2023).
cardiac hypertrophy (3 papers, 2023 to 2025). "Importantly, S100A9 deficiency alleviated TAC-induced cardiac hypertrophy and dysfunction in the early stage of TAC." (PMID 40860162, 2025). "Given that cardiac hypertrophy is one of the key mechanisms for the progression of HF 22, we investigated the effects of global S100A9 deficiency on this pathological process in WT and S100A9-KO mice." (PMID 40860162, 2025). "Collectively, these findings suggested that S100A9 in myeloid cells contributes to TAC-induced cardiac hypertrophy and dysfunction." (PMID 40860162, 2025). "Collectively, these results suggested that S100A9 induces adaptive cardiac hypertrophy and dysfunction at an early stage of disease." (PMID 40860162, 2025). "Taken together, these results suggested that the deletion of S100A9 mitigates TAC-induced cardiac hypertrophy and HF." (PMID 40860162, 2025). "Overall, these findings indicated that TAC-induced infiltration of macrophages highly expressing S100A9 is critical for the induction of maladaptive cardiac hypertrophy and the progression of HF." (PMID 40860162, 2025). "Other studies have shown that the β-AR agonist ISO also increased S100a9 expression in myocardial injury, and autophagy activity was also significantly reduced in myocardial hypertrophy induced by ISO." (PMID 37723445, 2023). "A research has confirmed that knockdown of S100a9 upregulates the expression of myocardial hypertrophy-related genes, such as ANP and β-MHC, in cardiomyocytes." (PMID 37723445, 2023). "We therefore validated whether S100A9 expression on myeloid cells is responsible for TAC-triggered cardiac hypertrophy in vivo." (PMID 40860162, 2025). "Additionally, treating WT mice with the S100A9 inhibitor ABR-238901 prevented TAC-induced cardiac hypertrophy-related dysfunction." (PMID 40860162, 2025). "To explore whether S100A8 or S100A9-mediated inflammation induces cardiac hypertrophy in the early phase of HF, we applied WT and S100A9-KO mice and subjected them to sham or TAC surgery for 1 week." (PMID 40860162, 2025). "Collectively, these data indicated that increased expression of S100A8 and S100A9 in neutrophils may play a major role in the early stage of adaptive cardiac hypertrophy, whereas S100A8 and S100A9 upregulation in macrophages may facilitate cardiac hypertrophy in the late stage of TAC-induced HF." (PMID 40860162, 2025). "Macrophage-specific S100A9 knockout significantly improves cardiac remodeling and cardiac dysfunction in diabetic mice, as evidenced by enhanced LVEF and reduced cardiac hypertrophy." (PMID 40384874, 2025).
Cerebral ischemia (3 papers, 2018 to 2025). Restriction of arterial blood supply to the brain associated with insufficient oxygenation to support the metabolic requirements of the tissue. "S100a8 and S100a9, the 11th most upregulated transcript in Trem2−/− mice in our data set, have been shown to play a role focal cerebral ischemia, with a deficiency in both transcripts resulting in diminished disease." (PMID 29040522, 2018). "Interestingly, S100A8 and S100A9 proteins were also detected within our study, confirming that the S100A8/A9 complex has a role in HIE, and has been suggested to be involved in the amplification of neuroinflammation, and cerebral ischemia-reperfusion injury." (PMID 37892154, 2023).
chronic liver failure (3 papers, 2021 to 2025). Liver failure that develops slowly and gradually for some time, possibly for years, often as the result of cirrhosis, or malnutrition. "Their findings revealed the role of M2-type macrophages in acute-on-chronic liver failure in regulating the necroptosis-S100A9-necroinflammation axis, pyroptosis of synergistic hepatoprotective mechanisms." (PMID 40406489, 2025).